BRAF (B-Raf proto-oncogene, serine/threonine kinase)
Diseases named in the same sentence as BRAF in open-access papers (continued):
Sharing a sentence is not in itself a finding about the gene and the disease.
thyroid cancer (continued). "Collectively, we proposed that the number of somatic mutations and BRAF mutation clonality should be added to the molecular risk stratification in thyroid cancer besides mutated genes." (PMID 37465126, 2023). "A major similarity between the Borealin-deficient mice and the human patient is the presence in thyroid cancer tissue of a BRAF-associated signature." (PMID 37964961, 2023). "Point mutations of the RAS genes and rearrangements of the RET gene are two other common mutations in thyroid cancer, both upstream of BRAF and acting through the MAPK and PI3K/AKT pathways." (PMID 37465126, 2023). "BRAF is a cytoplasmic serine-threonine protein kinase and commonly mutated in thyroid cancer and mutations in BRAF result in constitutive activation, thus promoting proliferation, tumorigenicity and dedifferentiation." (PMID 38076095, 2023). "Such a strategy will likely be able to target thyroid cancer disease progression in the BRAF mutated cases that constitute the majority of aggressive PTCs." (PMID 36982542, 2023). "In particular, BRAF mutations are detected in approximately 30%-60% of thyroid cancers, with papillary thyroid carcinomas showing mutation rates of up to 70% or more." (PMID 38313845, 2023). "Considering that the reactivation of MAPK/ERK pathway is a major cause of the resistance to BRAF kinase inhibitors such as PLX4032, we next determined the impact of DSF/Cu on the response of BRAF-mutated thyroid cancer cells to PLX4032." (PMID 36834830, 2023). "Antitumor effects of DSF/Cu on BRAFV600E-mutated thyroid cancer cells and its effect on the response of these cells to BRAF kinase inhibitor PLX4032 were systematically assessed by a series of in vitro and in vivo functional experiments." (PMID 36834830, 2023). "The growth inhibitory effects of the Src inhibitor, dasatinib, in combination with the MEK1/2 inhibitor trametinib were analyzed in 23 thyroid cancer cell lines expressing clinically relevant mutations (BRAF, RAS, RET/PTC1)." (PMID 36672327, 2023). "The BRAF V600E mutation in exon 15 of the BRAF gene has been studied in different cancers, including thyroid cancers." (PMID 36975440, 2023). "The change from valine (V) to glutamic acid (E) at codon 600 of the BRAF gene (BRAFVal600Glu) is the most commonly reported mutation in thyroid cancer." (PMID 36733350, 2023). "We explored the clonal architecture of BRAF mutation, the most frequently actionable mutation in thyroid cancer." (PMID 37465126, 2023). "It is worth noting that thyroid cancer patients with mutations in PIK3CA or AKT1 almost always also have BRAF mutations, indicating an interaction between the RAS/BRAF/MAPK pathway and the PI3K/AKT pathway in driving thyroid cancer development." (PMID 38313845, 2023). "The number of somatic mutations, TERT promoter mutations, and the clonal architecture of BRAF mutations should be considered in the risk stratification of thyroid cancer." (PMID 37465126, 2023). "In previous studies on the molecular genetic mechanisms of thyroid cancer, BRAF mutations were found to be the most frequently occurring mutations detected in 60-70% of papillary thyroid cancer (PTC) and 41-45% of anaplastic thyroid cancer (ATC) 1-3." (PMID 37325052, 2023). "Presence of a BRAF V600E mutation, the most common driver mutation in the spectrum of follicular cell derived thyroid cancers, can confer susceptibility to selective RAF kinase inhibitors in some cancer lineages." (PMID 36909304, 2023). "Previous review has shown that “Despite a high specificity for thyroid cancer, BRAF p.V600E mutation has a low overall sensitivity and therefore has a limited diagnostic value as a single screening test ”." (PMID 36070149, 2023). "A significant association was observed between thyroid stimulating hormone receptor (TSHR) gene methylation and positive BRAF V600E mutation cases in thyroid cancer." (PMID 36975440, 2023).
thyroid cancer (continued). "CD44v6-expression levels in the thyroid carcinoma cell lines were more heterogenous compared to patient samples, while BRAF mutational status was in line with the original tumor type." (PMID 38076095, 2023). "With its reduced costs, there are increasing applications for its use, particularly in the space of emerging small, targetable therapeutics for advanced thyroid cancers, particularly those with variants in BRAF, RET or kinase fusions." (PMID 37510219, 2023). "PTC with BRAF V600E mutation showed heightened MC infiltration, as BRAF mutation was bound up with the deterioration of thyroid carcinoma." (PMID 37345200, 2023). "Recently, numerous studies investigated the association between BRAF mutation and (central) cervical lymph node metastasis in thyroid cancer." (PMID 35402238, 2022). "In thyroid cancer patients treated with selective BRAF inhibitors, the emergence of acquired mutations in RAS genes has been described as a resistance mechanism." (PMID 35600349, 2022). "The current American Thyroid Association (ATA) guidelines recommend tumor BRAF status to assist in thyroid cancer stratification, with its presence placing a patient at greater risk of more aggressive disease." (PMID 36009596, 2022). "Most of the BRAF mutations occur in the position of the T1799A and others, including the mutation in the K601E in thyroid cancer." (PMID 36267655, 2022). "Previous studies reported marked increases in ERK signaling in BRAF-mutant thyroid cancer and found it to be associated with cancer development and treatment." (PMID 35464760, 2022). "It has been suggested that these different genetic alterations contribute to the progression of thyroid cancer with the presence of BRAF mutations predicting faster growth rate, spread, and higher cancer mortality." (PMID 36242015, 2022). "Li Fei’s research suggested that BRAF mutations were associated with multifocal thyroid cancer, extrathyroidal extension, lymph node metastasis, and advanced stages regardless of age." (PMID 36004350, 2022). "The most well-known genetic alteration is the BRAF V600E transversion, which is the most common BRAF mutation in thyroid cancer and is now used clinically to assess the risk of thyroid cancer metastasis and prognosis." (PMID 35464760, 2022). "We performed YAP1 staining in tissue microarrays of human thyroid cancers: 80% of patient samples with BRAF mutations and 60% with RAS mutations had NU-YAP." (PMID 36476495, 2022). "Several mutations, including RAS or RET, as well as BRAF signaling, are associated with thyroid cancer." (PMID 35630083, 2022). "Regarding Snail-1, the involvement of the B-Raf proto-oncogene (BRAF) gene was highlighted, linked with chemoresistance in thyroid cancer, and the role of epigenetic regulation was emphasized." (PMID 35873564, 2022). "For thyroid cancer the author found an interaction between BRAF and PIK3CA mutations which has been previously reported." (PMID 36275468, 2022). "The proportion of the most frequent BRAF mutation c.1799 T>A p.V600E significantly varies within the range of values below 10% in bladder cancer to over 90% in thyroid cancer." (PMID 37065428, 2022). "For example, since the early 2000s the BRAF gene mutation has been widely used as a hot diagnostic and prognostic marker for thyroid cancer in clinical practice, and the BRAF mutation test has been shown to improve diagnostic sensitivity to thyroid cancer." (PMID 36313748, 2022). "BRAF mutations are the most common genetic alterations in thyroid cancer (59.7%), while RET fusions are present in about 10%–20% of differentiated thyroid cancer." (PMID 36091770, 2022). "The BRAF V600E mutation is the most common mutation in thyroid cancers, and it is often associated with tumor aggressiveness and a poor prognosis." (PMID 36612117, 2022). "The analysis showed that BRAF is the most frequently mutated gene and is carried by approximately 60% of thyroid cancer patients." (PMID 35123502, 2022).
thyroid cancer (continued). "The BRAF V600E mutation is the most common genetic alteration found in thyroid cancer, particularly PTC, and is associated with more aggressive disease." (PMID 36242015, 2022). "The results confirmed that “epithelial cell proliferation”, “apoptosis” and “selective autophagy” were closely associated with this BRAF mutant in these thyroid cancer patients." (PMID 35123502, 2022). "BRAF T1799A mutation is the most common genetic variation in thyroid cancer, resulting in the production of BRAF V600E mutant protein reported to make cells resistant to apoptosis." (PMID 35748101, 2022). "In the thyroid cancer samples BRAF mutations co-occurred less frequently than expected with mutations in NRAS, HRAS, RET, PTEN, NF1 and KRAS." (PMID 36275468, 2022). "Fine-needle aspiration was performed on this patient to diagnose thyroid cancer by cytology with BRAF-mutated." (PMID 35634276, 2022). "Thyroid cancer cell lines with BRAF V600E mutation have higher PD-L1 mRNA expression compared to BRAF wild-type cell lines." (PMID 35992118, 2022). "A gene set enrichment analysis (GSEA) showed the signaling pathways associated with BRAF mutations in thyroid cancer patients." (PMID 35123502, 2022). "As BRAF gene mutations were highly correlated with thyroid cancer, our results also showed that microcalcification, hypoechogenicity, lobulated margins, and vertical position were significantly associated with BRAF gene mutations." (PMID 36160023, 2022). "Then, we confirmed that higher WT1 levels were closely related to worse prognosis in thyroid cancer patients with BRAF mutation." (PMID 35123502, 2022). "As the most common genetic alteration in thyroid cancer, BRAF-V600E mutation existed in 57% patients from TCGA-THCA dataset." (PMID 36387901, 2022). "For thyroid cancer, BRAF mutations and somatic copy number variation (CNV) are the most common genetic events." (PMID 36313748, 2022). "The efficacy of these agents in DTC patients seems promising, especially in the light of the overall high frequency of BRAF mutations in follicular-derived thyroid cancer." (PMID 35600349, 2022). "The results verified that “epithelial cell proliferation”, “apoptosis” and “selective autophagy” were closely associated with BRAF mutations in thyroid cancer patients." (PMID 35123502, 2022). "For 20-30% of thyroid nodules that cannot be definitively diagnosed by fine needle aspiration (FNA), thyroid cancer is highly suspected if a BRAF gene mutation is detected." (PMID 36713542, 2022). "Several previous studies, based on the TCGA data for thyroid cancer, have found that immune scores were associated with BRAF mutations, immune checkpoint expression, and prognosis." (PMID 36675746, 2022). "Next, the prognotic role of WT1 was assessing between BRAF mutated and BRAF wild-type thyroid cancer patients." (PMID 35123502, 2022). "TERT promotor methylation and BRAF V600E mutation are associated with PD-L1 expression in primary thyroid cancer." (PMID 36293435, 2022). "In the present cohort, 39.4% of thyroid cancers with these high‐risk mutations were detected, including five cases of BRAF V600E mutation (one combined with TERT mutation), two cases of TERT mutations and seven gene fusions." (PMID 35247035, 2022). "BRAF gene is the mutated gene in most thyroid cancers, but the clinical manifestations of some thyroid cancers are definitely different." (PMID 35865459, 2022). "The BRAF is the most prevalent mutation in thyroid cancer, which occurs in more than 50% of papillary thyroid cancers (PTCs) and approximately 45% of anaplastic thyroid cancer." (PMID 35646190, 2022). "The BRAF is the most prevalent genetic mutation in thyroid carcinoma, occurring in more than 50% of papillary thyroid cancers (PTCs)." (PMID 35646190, 2022).
thyroid cancer (continued). "The majority of the patients were identified as having mutations in BRAF-V600E and were most predominant in thyroid carcinoma, colon cancer, and skin cancer." (PMID 36267655, 2022). "In another study from Japan, 31 Japanese and 48 post-Chernobyl Ukrainian thyroid carcinomas involving children, adolescents and young adults were evaluated for BRAF V600E and RAS mutations." (PMID 36553142, 2022). "An activating BRAF mutation is the most common genetic event in thyroid carcinoma, found in roughly 45% of papillary thyroid carcinomas." (PMID 36329478, 2022). "The BRAF oncogene is mutated in different cancer types, among which MM and thyroid carcinoma (THCA) are prominent." (PMID 35272691, 2022). "The expression of PDL-1 was also linked to clinicopathological features, such as mutations of TERT promoter and BRAF showing progression of advanced thyroid cancer." (PMID 34944814, 2021). "In the literature, the impact on the fitness effect of the BRAF V600E mutation is likely different among tumor types, including thyroid cancer, skin cutaneous melanoma, and lung adenocarcinoma." (PMID 34424899, 2021). "The density of mutations is higher in poorly differentiated thyroid cancers, BRAF and RAS point mutations being the most frequent alterations." (PMID 34638232, 2021). "BRAF, specifically BRAF V600E, is the most common mutation, accounting for 60% of these mutations in thyroid cancer, with the highest incidence in PTC." (PMID 34734568, 2021). "Some research has reported BRAF mutation associated with MAPK activation affect GαS signaling to inhibit iodine uptake of thyroid cancer cells." (PMID 34650915, 2021). "This article reviews the importance of thyroid cancer epigenetic modification and BRAF gene mutation in the treatment of thyroid cancer." (PMID 34923978, 2021). "Consistently with our data, two recent studies reported the acquisition of secondary RAS gene mutations in thyroid cancer patients treated with BRAF inhibitors." (PMID 34072194, 2021). "In the same way, it is possible to apply the same pipeline to other cancers, for example by adding thyroid cancer cell lines, sometimes BRAF-mutated, to the analysis." (PMID 33507915, 2021). "Immunostaining, using a mouse monoclonal antibody VE1, specific for the most prevalent mutation in thyroid cancer BRAF V600E, has shown excellent concordance with molecular testing." (PMID 35008368, 2021). "The most common mechanism of BRAF activation in thyroid cancer involves a point mutation that comprises a substitution of thymine to adenine at nucleotide position 1799, which results in replacement of a valine-to-glutamate at residue 600 (Val600Glu)." (PMID 33669363, 2021). "Papillary thyroid carcinoma is the most common cancer of the thyroid characterized by a high incidence of BRAF V600E mutations." (PMID 34307217, 2021). "Although the BRAF V600E (c.1799T>A) mutation is the most common type of genetic mutation in thyroid cancer, the BRAF L597Q (c.T1790A) mutation is extremely rare." (PMID 33578538, 2021). "The BRAF V600E (chr7:140453136 c.1799T>A) mutation was located in situ of thyroid cancer, but the BRAF L597Q (chr7:140453145 c.1790T>A) mutation was located in the brain metastases." (PMID 33578538, 2021). "Studies also reported a positive correlation between RARB2 promoter methylation and the BRAF gene V600E mutation in thyroid cancer." (PMID 34923978, 2021). "The BRAF V600E activating mutation is arguably the most well understood and studied genetic alteration in thyroid cancer." (PMID 34335481, 2021). "Several inhibitors targeting BRAF mutation, such as vemurafenib and dabrafenib, have been discovered and show a dramatic response in advanced thyroid cancer patients harboring BRAF V600E mutation." (PMID 34221969, 2021). "Thirty-two somatic mutations were identified exclusively in known thyroid cancer genes (BRAF, KRAS, NRAS, and TERT)." (PMID 33821390, 2021).
thyroid cancer (continued). "The utility of cfDNA or ctDNA for detecting alterations in a single gene, commonly BRAF V600E mutation, or multiple genes in thyroid cancer, has been evaluated." (PMID 35008368, 2021). "The BRAF-V600E mutation constitutes 98–99% of all BRAF mutations found in thyroid cancer, but other alterations, including other point mutations, in-frame insertion/deletion and rearrangements, have been reported." (PMID 33572167, 2021). "We analyzed the TCGA thyroid cancer study for commonly affected genes and found a high mutation rate in only one single point mutation: the BRAF V600 mutation." (PMID 34630336, 2021). "Despite our detailed understanding of the molecular underpinning of the tumorgenesis in thyroid cancer, clinically it is often difficult to explain why one BRAF mutated RAI-R TC will respond to an inhibitor and another will not." (PMID 34335481, 2021). "Although the role of RAS and BRAF mutations in thyroid cancer have been partially clarified,but the pathogenesis and molecular mechanisms of thyroid cancer remain to be elucidated." (PMID 34923978, 2021). "Specific mutations in thyroid cancer cells, such as BRAF V600E, have been described as EMT modulators, enhancing thyroid cancer progression features." (PMID 34680488, 2021). "Despite a high specificity for thyroid cancer, BRAF V600E mutation has a low overall sensitivity and therefore has a limited diagnostic value as a single screening test." (PMID 34070605, 2021). "Papillary thyroid cancer (PTC) accounts for 70% of thyroid cancers, and 60% of PTCs carry canonical BRAF (V600E) mutations." (PMID 34475951, 2021). "Although BRAF V600E has a favorable diagnostic value in thyroid cancer, it only provides evidence for PTC or PTC-derived poorly differentiated thyroid carcinoma." (PMID 34322384, 2021). "In contrast, more than 40% of the thyroid cancers show a BRAF V600 mutation which is associated with the papillary tumor type and found rarely in follicular thyroid cancer type." (PMID 35251119, 2021). "The development of thyroid cancer involves multiple genetic and epigenetic alterations such as point mutation of the BRAF and RAS genes which seem to be linked to specific etiologic factors like exposure to ionizing radiation and chemical mutagenesis." (PMID 34289835, 2021). "In BRAF-mutated thyroid cancer cells, inhibition of BRAFV600E signaling was reported to induce autophagy as an adaptive response to endoplasmic reticulum (ER) stress, as assessed using immunoblotting analysis in combination with electron microscopy." (PMID 34298710, 2021). "Genetic and epigenetic alteration of the RAS–RAF–MEK–MAPK–ERK pathway, and mutations in NRAS, KRAS, and BRAF, have been shown to strongly influence the development of thyroid cancers." (PMID 33915745, 2021). "Of all genetics associated with well-differentiated thyroid cancer, BRAF and TERT mutations are the most robust prognosticators of aggressive disease." (PMID 34702207, 2021). "In summary our in silico analysis for drug prediction response based on alterations described in the TCGA data suggested BRAF inhibitors as the most promising target for most classic and tall-cell variants of thyroid cancer." (PMID 34630336, 2021). "Most extensively investigated and clinically approved targeted therapies in thyroid cancer include the tyrosine receptor kinase inhibitors that target antiangiogenic markers, BRAF mutation, PI3K/AKT, and MAPK pathway components." (PMID 34944814, 2021). "In advanced thyroid cancer, BRAF mutations were less frequent, whereas the RAS mutations were more so in comparison to the PTCs." (PMID 34944814, 2021). "In thyroid cancer cells, driver mutation of the BRAF gene activates the mitogen-activated protein kinase pathway, which induces overexpression of the E-twenty-six (ETS) transcription factor." (PMID 34070093, 2021). "In thyroid cancer, mutations in activated BRAF, RAS, and RET-PTC fusion genes can cause the stimulation of the MAPK signaling pathway." (PMID 34689819, 2021).